TRIB3 (tribbles pseudokinase 3)
Diseases named in the same sentence as TRIB3 in open-access papers (continued):
Sharing a sentence is not in itself a finding about the gene and the disease.
tumor (continued). "The interruption of this p62/TRIB3 interaction attenuates xenograft tumor growth and metastatic dissemination, confirming the role of TRIB3 in this context as an oncogene." (PMID 33920424, 2021). "Thereby, the p62/TRIB3 2 interaction induces the blocking of the autophagic flux that interestingly leads to the accumulation of several tumor-promoting factors." (PMID 33920424, 2021). "Depletion of TRIB3 results in drastically decreased expression of several tumor-promoting factors, including EGFR, across cancers." (PMID 32694521, 2020). "Disruption of the interaction between TRIB3 and p62 resulted in tumor suppression in an animal model." (PMID 33334065, 2020). "The incidence rate of tumor formation was 12.5% (one out of eight mice obtained from two independent experiments) for sh-TRIB3-transduced tumorsphere cells and 100% for the shLacZ group." (PMID 33334065, 2020). "Significantly, the tumor metastasis effects of TRIB3 knockdown were partially reversed when autophagy was inhibited by CQ." (PMID 33203798, 2020). "Several groups have demonstrated that TRIB3 plays a critical role in the regulation of tumorigenesis and tumor progression in recent years." (PMID 33203798, 2020). "After four weeks, we found that sh-TRIB3 significantly reduced the tumor volume and tumor weight of sh-TRIB3 mice compared with those of the control group, while these effects were abolished by CQ treatment." (PMID 33203798, 2020). "After four weeks, we found that sh-TRIB3 significantly reduced the tumor volume and tumor weight of sh-TRIB3 mice compared with the control group." (PMID 33203798, 2020). "Use of a peptide to disturb the TRIB3-MYC interaction together with doxorubicin reduces the tumor burden in MycEμ mice and patient-derived xenografts." (PMID 33298911, 2020). "A tumor suppressor function of TRIB3 has been proposed via the inactivation of AKT1 or nuclear factor kappa B subunit (NF-κB) through direct binding." (PMID 33334065, 2020). "TRIB3 has been shown to interact with SMAD family member 3 (SMAD3) to promote transforming growth factor beta (TGFβ)-induced tumor cell migration and invasion." (PMID 33334065, 2020). "Depletion of tribbles pseudokinase 3 (TRIB3) is known to suppress the expression of several tumor-promoting factors, including EGFR." (PMID 32694521, 2020). "TRIB3 has recently been identified as a stress sensor in response to various tumor microenvironments or niche-rich stressors, including amino acid or glucose deficiency, insulin, unfolded protein accumulation in the endoplasmic reticulum, and oxidative damage." (PMID 31844113, 2019). "Disruption of the interaction between TRIB3 and p62 resulted in a tumor suppression consequence in an animal model." (PMID 30678233, 2019). "TRIB3 binds SMAD3 to promote tumor cell migration and invasion and activates MAPK and TGFβ pathways." (PMID 29757932, 2018). "TRIB3 was elevated in tumor lesions of patients with NSCLC which correlated with poor prognosis of NSCLC." (PMID 29367413, 2018). "Knock-down of TRIB3 expression in tumor cells significantly inhibits the invasive and metastatic ability of the cells by promoting the mesenchymal-epithelial transition." (PMID 28871113, 2017). "In tumor cells, TRIB3 augments TGF-β1-SMAD3-mediated transcriptional activity and cellular functions by physically interacting with SMAD2/3." (PMID 28871113, 2017). "Nupr1 has also been implicated in mediating cannabinoid-induced apoptosis of tumor cells through upregulation of the ERS-related genes ATF4, Chop and Trib3 (tribbles pseudokinase 3)." (PMID 27031958, 2016). "They further find that silencing TRIB3 not only decreases the basal levels of critical tumor‐promoting factors, but also protects them from the IGF‐1 induction." (PMID 27038142, 2016).
tumor (continued). "Trib3 was shown to enhance the tumorigenicity of a variety of tumor cell lines and xenografts via a mechanism that involved dysregulation of AKT phosphorylation by the mTORC2 complex and subsequent inactivation of the transcription factor FOXO3." (PMID 27191957, 2016). "Their results suggest that TRIB3 plays a crucial role in tumorigenesis and tumor progression in mice, particularly in diabetic mice." (PMID 27038142, 2016). "In mice and humans, Trib3 levels are regulated by nutrient availability in skeletal muscle cells, beta-cells, adipocytes, and tumor cells, highlighting a possible role in the regulation of metabolic flux in insulin-sensitive tissues." (PMID 25329475, 2014). "Data supports that the CHOP/ATF4 arm of the unfolded protein response (UPR) which is responsible for TRIB3 upregulation during hypoxia protects tumor cells during hypoxia." (PMID 23185332, 2012). "On the other hand, the finding that high TRIB3 mRNA is associated with a poor prognosis suggests that any mechanism that is involved in the induction of TRIB3 mRNA is also involved in tumor progression and/or treatment resistance." (PMID 23185332, 2012). "TRIB3 induction is most pronounced at a moderate oxygen concentration and TRIB3 seems involved in hypoxia response of tumor cells." (PMID 21864376, 2011). "TRIB3 staining was specifically seen in the hypoxic regions of the tumor, distant from the blood vessels." (PMID 21864376, 2011). "Since the death executor TRIB3 is induced by CHOP, our finding that LAP attenuated and LIP augmented the expression of TRIB3 in the tumor suggests that LAP promotes tumor progression by attenuating CHOP-mediated cell death." (PMID 20209087, 2010). "The reduced expression of the CHOP-induced death executor TRIB3 indicated that the tumor progression and the inhibition of ER stress–triggered cell death in vitro share a common mechanism, mediated by C/EBP-β." (PMID 20209087, 2010). "In biological assessment, this study showed that TRIB3 expression was related to tumour growth in several gastrointestinal cancer cell lines." (PMID 19904274, 2009). "The high-expression group comprised patients who had a level of TRIB3 expression higher than the median value for TRIB3/GAPDH expression in tumour regions compared with normal regions (n=101); other patients were assigned to the low-expression group (n=101)." (PMID 19904274, 2009). "In ARMS, TRIB3 expression is markedly elevated and has been specifically linked to the presence of the PAX3-FOXO1 fusion oncoprotein, a defining molecular hallmark of this aggressive tumor subtype." (PMID 40508013, 2025). "Additionally, analysis of tumor vasculature density and area demonstrated that TRIB3 overexpression promoted angiogenesis, resulting in increased sinusoidal vasculature within tumors." (PMID 39932456, 2025). "In addition, the number of PCNA-/METTL3-/TRIB3-positive cells was higher in tumor samples from the Tan-IIA treatment group." (PMID 39910904, 2025). "In addition, HCC patients exhibiting elevated tumor expression of TRIB3 frequently displayed poor responsiveness to sorafenib therapy." (PMID 39932456, 2025). "Moreover, the protein levels of METTL3 and TRIB3 were significantly suppressed in Tan-IIA treatment group-derived tumor samples compared to those from the control group." (PMID 39910904, 2025). "Therefore, sorafenib‐induced TRIB3 triggered secondary resistance via remodeling the tumor immune microenvironment." (PMID 39932456, 2025). "TRIB3 knockdown was observed to mitigate tumor growth in a subcutaneous xenograft model." (PMID 38429254, 2024). "In conclusion, the study identifies TRIB3 as a tumor promoter in HNSCC via attenuating ferroptosis." (PMID 38429254, 2024). "Furthermore, the study demonstrated that the molecular inhibitor hesperidin, targeting TRIB3, not only reduced cell malignancy but also induced ferroptosis, thereby suppressing tumor growth." (PMID 38429254, 2024).
tumor (continued). "Prior research have illuminated the tumor-promoting effect of TRIB3 in various tumors." (PMID 38429254, 2024). "Additionally, inducible silencing of TRIB3 significantly delayed tumor growth and improved overall survival in vivo." (PMID 38581035, 2024). "Besides, inhibiting TRIB3 to turn “cold tumor” hot has also been proved to be an effective therapeutic strategy for BC." (PMID 39881875, 2024). "The knockdown of TRIB3 decreased the proliferation potential, invasion capacity and colony formation ability of A498 cells and enhanced the apoptosis and autophagy process of A498 cells, which indicated that TRIB3 acted as a pro-tumor factor in RCC." (PMID 38006403, 2023). "Therefore, our analysis focused on understanding the TRIB3 role in specific phenotypes of tumor epithelial cells, the latter of which was exacted from scRNA datasets and further visualized after dimensionality reduction." (PMID 37153569, 2023). "As violin plots represent, tumors in high TRIB3 expression patients had fewer stromal and immune cells than those with low TRIB3 expression, i.e., tumors in patients with high TRIB3 expression had a higher proportion of malignant tumor cells." (PMID 38235126, 2023). "Multivariate Cox analysis showed that age (HR=1.028, 95% CI = 1.014 to 1.044, p<0.001], TRIB3 expression (HR=1.267, 95% CI = 1.069 to 1.503, p=0.006), and tumor stage (HR=1.484, 95% CI = 1.232 to 1.787, p<0.001) were all independent prognostic factors for HNSC." (PMID 38235126, 2023). "Recently, much research has found that TRIB3 plays a crucial role in tumor immune regulation." (PMID 38235126, 2023). "Furthermore, TRIB3 has been indicated to promote various tumor malignant phenotypes, such as tumor cell proliferation, invasion, and epithelial-mesenchymal transition." (PMID 38235126, 2023). "More investigations on PRPCDGs (such as TRIB3) could get further insights into mechanisms of tumor progression and provide potential targets for RCC treatment." (PMID 38006403, 2023). "We evaluated the role of TRIB3 in ccRCC using publicly available data from The Cancer Genome Atlas and analyzed its relationship with the tumor microenvironment; moreover, we used gene knockout and overexpression techniques to detect the effects of TRIB3 on the biological behavior of ccRCC cells." (PMID 35726370, 2022). "On the basis of our results, we suggested that suppression of TRIB3-AKT axis could efficiently impair tumor growth and improve the outcome of chemotherapy in NSCLC." (PMID 35473511, 2022). "In addition to known tumor-promoting genes, e.g., c-MYC, YAP1, RAD51B, TRIB3, SLC17A9, JADE1, we found that NAPRT, encoding a key enzyme for NAD+ biosynthesis from nicotinic acid, was also suppressed in HCC cells by the BRD4 inhibitor." (PMID 35399501, 2022). "Notably, TRIB3 was expressed at significantly higher levels in tumor tissue than in normal kidney tissue (p < 0.001)." (PMID 35726370, 2022). "Furthermore, we revealed the role of TRIB3 in the malignant progression, immune landscape characteristics, tumor microenvironment, and clinical outcomes of patients with ccRCC." (PMID 35726370, 2022). "Overall, our study revealed that elevated TRIB3 expression represents a promising prognostic marker for ccRCC patients and may play a key role in tumor microenvironment modulation." (PMID 35726370, 2022). "Also, tribbles pseudokinase 3 (TRIB3) regulated tumor progression by activating the MAPK signaling pathway to accelerate the proliferation, migration, and invasion of RCC." (PMID 35938021, 2022). "Meanwhile, TRIB3 was involved in tumor progression and was related to a poor prognosis." (PMID 36120545, 2022). "In this study, we found that the expression of TRIB3 increased with the advancement of clinical stage, pathological grade, primary tumor size, distant metastasis, and patient fustat, suggesting that TRIB3 promotes ccRCC progression and increases the risk of invasion and deterioration of ccRCC." (PMID 35726370, 2022).
tumor (continued). "GSEA showed that TRIB3 was enriched in distinct pathways for the two tumor phenotypes." (PMID 35726370, 2022). "Studies have shown that TRIB3 might be an oncogene or a tumor suppressor depending on the specific tumor types." (PMID 34957220, 2021). "In addition, TRIB3 can contribute to tumor progression via the positive regulation of signaling pathways like Notch and TGF-β." (PMID 33920424, 2021). "Indeed, as TRIB3 interacts with and regulates the activity of many key signaling components, it can act as a tumor-suppressor or oncogene in a context-dependent manner." (PMID 33920424, 2021). "Moreover, when comparing tumor with adjacent normal tissues, higher TRIB3 and β-catenin expression, along with proteins co-localization, was observed." (PMID 34198908, 2021). "Moreover, they also observed up to 400-fold overexpression of TRIB3 mRNA in human tumor tissues from primary tumors with different TNM stages versus normal colonic mucosa." (PMID 34198908, 2021). "Specifically, TRIB1 and TRIB3 might be considered candidates as predictive markers of tumor metastasis development." (PMID 34198908, 2021). "The reduction of tumour growth can be observed in dissimilar models of tumour xenografts, but not in p8-deficient tumour models that lack upregulation of the p8/TRIB3 pathway." (PMID 33802014, 2021). "In addition, the phosphorylation of STAT3/5 and EGFR, as well as the expression of total EGFR, PKCα, TRIB3, and core pluripotency factors, were reduced in tumor tissue samples from NCI-H1975 inoculated mice treated with SAH-JGZ4." (PMID 32694521, 2020). "We further checked the protein expression of TRIB3, ALDH1A1, and c-MYC in lysates of xenografted tumors and results showed that TRIB3 was slightly decreased in the only one small engrafted tumor of TRIB3-knockdown AN3CA cells, while the expression levels of ALDH1A1 and c-MYC were greatly reduced." (PMID 33334065, 2020). "Indeed, depletion of either PKCα or WWP1 abrogated TRIB3-enhanced proliferation, invasion, and tumor growth." (PMID 32694521, 2020). "In addition, many studies describe Trib3 as a key factor in mediating the anti-tumor effect of cannabinoids." (PMID 33210603, 2020). "Similar to our in vitro results, immunohistochemical analyses of the lungs of KRASLA2 mice showed decreased pAKT and increased TRIB3 expression in tumor mass of PIERCE1 KO mice, implying that ablation of PIERCE1 suppresses lung tumorigenesis with impaired AKT activity in vivo." (PMID 32728173, 2020). "Our results demonstrated that TRIB3 knockdown significantly reduced tumor metastasis in vivo." (PMID 33203798, 2020). "TRIB3 could interact with SMAD family member 3 (SMAD3) to promote transforming growth factor (TGF)-β induced tumor cell migration and invasion." (PMID 30678233, 2019). "On the other hand, TRIB3 has been suggested as a sensor of tumor microenvironment." (PMID 30678233, 2019). "Furthermore, TRIB3 has a pivotal role in insulin signaling transduction pathway, and the DM-induced tumor progression." (PMID 29367413, 2018). "The tumor inhibitory role of TRIB3 is connected to ER stress and AKT signaling pathway." (PMID 30176898, 2018). "Hence, these authors find that there is a positive correlation between TRIB3 and activation of insulin signaling in tumor tissues." (PMID 27038142, 2016). "We hypothesized that TRIB3 could be an important protein by determining the tumor cell fate under stressed conditions." (PMID 21864376, 2011). "Furthermore, we assessed TRIB3 expression in recurrent HCC patients who had undergone sorafenib therapy prior to secondary resection, revealing a marked elevation of TRIB3 in recurrent tumor tissues compared to matched primary resected samples (n = 15, p < 0.001)." (PMID 39932456, 2025). "Notably, TRIB3 is key stress regulators in a variety of tumors because its C-terminal domain can interact with ubiquitin ligases and various other proteins to promote tumor progression, such as AKT1, β-catenin, SQSTM1, TRIM8, EGFR, and TCF4." (PMID 39881875, 2024).
tumor (continued). "Elevated TRIB3 expression is a promising prognostic marker for ccRCC patients and may play a key role in tumor microenvironments, which indicates a novel molecular mechanism involving TRIB3 in ccRCC and identifies TRIB3 as a novel therapeutic target for ccRCC therapy from bench to clinic." (PMID 35726370, 2022). "In addition, expression inhibition of TMPO, TOP2A, RFC3, GINS1, and CKS2 genes could prevent tumor growth and TRIB3 expression suppression would be a favorable target for anti−angiogenic therapy." (PMID 34249670, 2021). "Indeed, depletion of either PKCα or WWP1 abrogated TRIB3-enhanced tumor sphere formation; while TRIB3 depletion-impaired tumor sphere formation could be rescued by overexpressing the of EGFRT654D mutant but not the EGFRT654A or EGFRT654D/K689R mutants." (PMID 32694521, 2020). "Furthermore, the tumor weight of TRIB3 knockdown EC tumorsphere cells was significantly reduced." (PMID 33334065, 2020). "In addition, silencing TRIB3 expression suppressed tumor growth and metastasis." (PMID 31844113, 2019). "Furthermore, TRIB3 promoted the tumor development of liver and lung in DM mice." (PMID 29367413, 2018). "Thus, we wanted to determine whether ectopic expression of TRIB3 or MTHFD2 could counteract the tumor suppressive activity of SOX7." (PMID 29757932, 2018). "Trib3 is a human homologue of Drosophila tribbles 3, which regulates cell growth, differentiation, oogenesis and metabolism by promoting ubiquitination-dependent degradation of other proteins, interacts with several transcriptional factors and is expressed in several tumours." (PMID 19904274, 2009). "Findings displayed the TRIB3 expression was related to the immune Scoring, ESTIMATES Scoring, stromal Scoring, and the purity of the tumor." (PMID 39869954, 2025). "We demonstrated the potential of TRIB3 as a prognostic indicator for poor outcomes in HNSCC, unveiling a novel mechanism by which it promotes tumor growth through the inhibition of ferroptosis." (PMID 38429254, 2024). "Overall, these results suggested that TRIB3 can promote the abnormal accumulation of lipids while inhibiting ER stress and consequent apoptotic death in RCC tumor cells." (PMID 38561354, 2024). "The role of TRIB3 in the tumor-initiating capacity of HNSCC cells was examined, and the impact of TRIB3 silencing-induced ferroptosis was further validated in vivo." (PMID 38429254, 2024). "TRIB3 potential as a poor prognosis factor for HNSCC was demonstrated, and unveiled a novel mechanism by which it promotes tumor growth by inhibiting ferroptosis." (PMID 38429254, 2024). "Data mining of the TCGA dataset revealed that chromosomal instability (CIN) tumors have lower TRIB2 and higher TRIB3 expression versus microsatellite instability (MSI)-high tumors, while TRIB1 levels are similar in both tumor types." (PMID 38254916, 2023). "We demonstrated that the tumor suppressive is mediated by both positively and negatively acting downstream effectors, including CBX6, TRIB3, ETV4 and FOS/JUN, where the first two also affect the differentiation status of Lp30 AML." (PMID 36631623, 2023). "The expression level of these genes differs significantly between the tumor and normal tissues, but CREB3L3 and TRIB3, and XBP1 are overexpressed, while PPP1R15A is expressed conversely." (PMID 37880674, 2023). "Furthermore, TRIB3 expression was significantly correlated with the T-stage, and patients with higher T-stage had significantly higher TRIB3 expression than lower T-stage patients, which suggests that TRIB3 expression is related to tumor growth and infiltration ability." (PMID 38235126, 2023). "Several studies have observed that TRIB3 is highly expressed in RCC, and the elevated TRIB3 expression in RCC patients was correlated with clinicopathologic features of the tumor and prognosis." (PMID 38006403, 2023).